PDLIM3 (PDZ and LIM domain 3)
Description:
May play a role in the organization of actin filament arrays within muscle cells.
Synonyms: ALP
Tractability: No criterion of Open Targets' tractability assessment is met for any kind of drug.
Gene: Protein-coding gene on chromosome 4 (185,500,660 to 185,535,507, reverse strand). Ensembl gene ENSG00000154553.
Subcellular location: Cytoplasm, myofibril, sarcomere, Z line
Subcellular location (Human Protein Atlas): Cytosol
Gene Ontology:
Molecular function: protein binding; actin binding; muscle alpha-actinin binding; cytoskeletal protein binding; structural constituent of muscle
Biological process: actin cytoskeleton organization; heart development; muscle structure development
Cellular component: cytosol; adherens junction; filamentous actin; stress fiber; Z disc; actin cytoskeleton
Genetic constraint (gnomAD): Loss-of-function variants: 23 observed, 30.43 expected, observed/expected ratio (o/e) 0.76, 90% interval 0.54 to 1.07. The upper end of that interval is the gene's LOEUF score, 1.07, which puts it in group 4 of 6, group 1 being the genes least tolerant of losing a copy. Missense variants: 425 observed, 469.29 expected, observed/expected ratio (o/e) 0.91, 90% interval 0.84 to 0.98. Synonymous variants: 165 observed, 178.42 expected, observed/expected ratio (o/e) 0.92, 90% interval 0.81 to 1.05.
Gene-disease validity (ClinGen):
ClinGen rates the evidence that PDLIM3 causes each of these diseases.
hypertrophic cardiomyopathy (autosomal dominant): Limited. A condition in which the myocardium is hypertrophied without an obvious cause.
dilated cardiomyopathy (autosomal dominant): Disputed. Cardiomyopathy which is characterized by dilation and contractile dysfunction of the left and right ventricles.
Homologues: Orthologues: chimpanzee PDLIM3 (99% identical), macaque PDLIM3 (95% identical), guinea pig PDLIM3 (94% identical), pig PDLIM3 (93% identical), rat Pdlim3 (93% identical), rabbit PDLIM3 (92% identical), dog PDLIM3 (90% identical), tropical clawed frog pdlim3 (76% identical), mouse Pdlim3 (66% identical), zebrafish pdlim3b (50% identical), zebrafish pdlim3a (43% identical). Paralogues in human: PDLIM1 (41% identical), PDLIM4 (38% identical), PDLIM2 (27% identical), LDB3 (27% identical), PDLIM7 (26% identical), PDLIM5 (25% identical), PRICKLE4 (14% identical).
Diseases named in the same sentence as PDLIM3 in open-access papers:
PDLIM3 is named in the same sentence as 46 diseases in open-access papers, as found by Europe PMC text mining. Sharing a sentence is not in itself a finding about the gene and the disease. The quoted sentences say what the papers report.
cardiomyopathy (4 papers, 2017 to 2022). A disease of the heart muscle or myocardium proper. "This protein is found in muscle cells and polymorphisms in PDLIM3 were earlier associated with systolic blood pressure and an increased risk of cardiomyopathy." (PMID 35740506, 2022). "The inclusion of PDLIM3 exon 6 is predicted to result in nonsense-mediated decay in cardiomyopathy, while CD36 exon 11 inclusion should result in protein truncation (AltAnalyze)." (PMID 28098235, 2017). "We identified genes with alternative splicing profiles that were common to cardiomyopathy (PDLIM3, CD36, CLDND1, TTN, FAM126a, TLR4, and CD59)." (PMID 28098235, 2017). "PDLIM3-specific up-regulation in Tibetan pigs might therefore increase cardiovascular permeability, promote vascular endothelial cell proliferation and migration, and increase the regulation of cardiovascular development to prevent the occurrence of cardiomyopathy." (PMID 28623314, 2017).
endometriosis (4 papers, 2022 to 2025). The growth of functional endometrial tissue in anatomic sites outside the uterine body. "In a previous study, we identified PDLIM3 as a specific biomarker for endometriosis that was associated with multiple immune cells." (PMID 37662927, 2023). "It is the first time that PDLIM3 has been linked to endometriosis." (PMID 35378934, 2022). "In a previous study, it was discovered that PDLIM3, a specific biomarker in endometriosis, was correlated with multiple immune cells, such as M2 macrophages, activated NK cells, and CD8+ T cells." (PMID 37662927, 2023). "High expression of PDLIM3 in endometriosis has also been reported in several previous bioinformatics studies with little supportive experimental evidence." (PMID 36339397, 2022). "The ability of PDLIM3 in discriminating endometriosis from the control samples demonstrated a favorable diagnostic value, with an AUC of 0.955 (95% CI [0.894–0.997])." (PMID 35378934, 2022). "We confirmed PDLIM3 was a specific biomarker in endometriosis (AUC = 0.955) and validated in the GSE120103 dataset (AUC = 0.836)." (PMID 35378934, 2022). "The expression levels of PDLIM3 in endometriosis tissue were notably higher than those in the normal tissue." (PMID 35378934, 2022). "The mRNA and protein expression level of PDLIM3 in endometriosis tissue was significantly higher than normal." (PMID 35378934, 2022). "In a word, our results strongly suggest that PDLIM3 plays a previously unidentified but critical role in pathogenesis and immune environment of endometriosis." (PMID 35378934, 2022). "Although several microarray and proteome analyses have already revealed high PDLIM3 expression in this regard, the exact role of PDLIM3 in endometriosis remains to be elucidated." (PMID 36339397, 2022). "Second, immune cell infiltration and the functions of PDLIM3 in endometriosis were inferred by bioinformatics analysis, and future prospective studies with larger sample sizes should be employed to validate our findings." (PMID 35378934, 2022). "Better understanding of PDLIM3 could have a highly beneficial impact on the clinical treatment and outcomes of endometriosis patients." (PMID 35378934, 2022). "Further study should be performed to confirm the function of PDLIM3 in endometriosis." (PMID 35378934, 2022). "Therefore, PDLIM3 became one of the potential specific biomarkers in endometriosis." (PMID 35378934, 2022). "Quantitative assessments of histological images clearly demonstrated higher expression levels of LY96, PDLIM3, PTGIS, and WISP2, proteins in tissues from patients with endometriosis, in line with integrative analysis results." (PMID 36339397, 2022). "According to western blot analysis, the protein levels of LY96, PDLIM3, and PTGIS were higher in the tissues of endometriosis patients." (PMID 36339397, 2022). "Third, the biomarker PDLIM3 in this study is derived from endometriosis tissue, which indicates that this biomarker is not suitable to be used for early clinical diagnosis." (PMID 35378934, 2022). "We found PDLIM3 had higher expression level in endometriosis group than normal control (qRT-PCR: n = 6 vs. 6; Western blot: n = 7 vs. 4)." (PMID 35378934, 2022).
idiopathic dilated cardiomyopathy (4 papers, 2019 to 2025). Decreased function of the heart associated with cardiac enlargement and congestive heart failure, of unknown cause. "Recently, SNPs in PDLIM3 and PDLIM5 have been implicated in the development of idiopathic dilated cardiomyopathy." (PMID 36531944, 2022).
medulloblastoma (4 papers, 2022 to 2025). A malignant, invasive embryonal neoplasm arising from the cerebellum. "PDLIM3 is highly expressed in the sonic hedgehog (SHH) group of medulloblastoma (MB) and in gastric cancer, while its expression is significantly reduced in prostate cancer." (PMID 40243891, 2025). "In the SHH subgroup of medulloblastoma, PDLIM3 expression is significantly higher than in normal brain tissue, and its loss impairs cilia formation, inhibiting tumor cell proliferation and growth." (PMID 40243891, 2025). "In medulloblastoma, studies have shown that the abnormal expression of PDLIM3 and four other genes leads to the abnormal activation of Hedgehog (Hh) signaling, which is an important diagnostic marker for medulloblastoma patients." (PMID 37894409, 2023). "In cancer, PDLIM3 has been identified as a candidate in a five-gene signature that can predict activated hedgehog signaling in medulloblastoma patient tissues." (PMID 36077609, 2022). "A high level of expression of PDLIM3 was reported in medulloblastoma, bladder, and tongue carcinoma." (PMID 35647201, 2022). "In medulloblastoma, high PDLIM3 gene expression was detected after hedgehog pathway activation, which could be an indication for using sonidegib treatment." (PMID 35647201, 2022). "Numerous studies have reported abnormal expression of PDLIM3 across various cancers, including its upregulation in gastric cancer, colon cancer, and the SHH subgroup of medulloblastoma, while significant downregulation has been found in prostate cancer." (PMID 40243891, 2025).
colon cancer (3 papers, 2013 to 2025). "In summary, these results indicated that the expression of CTHRC1, FBN2, NTM, PDGFC, and PDLIM3 is associated with tumor progression and metastasis of colon cancer cells." (PMID 35991839, 2022). "This indicated that the expression levels of CTHRC1, FBN2, NTM, PDGFC, and PDLIM3 genes are associated with the modulation of immune and stromal activity in the colon cancer tumor microenvironment." (PMID 35991839, 2022). "Interestingly, we found that the expression levels of CTHRC1, FBN2, NTM, PDGFC, and PDLIM3 are positively correlated with the ssGSEA scores of metastatic-promoting genes in colon cancer (Spearman’s correlation test, p < 0.001)." (PMID 35991839, 2022). "Since the upregulated group of CTHRC1, NTM, PDGFC, PDLIM3, and SLC16A3 and the downregulated group of FBN2 genes are consistently correlated with the shorter survival time in TCGA and GEO datasets, we investigated the association of these genes with immune score and stromal scores in colon cancer." (PMID 35991839, 2022). "The upregulation of CTHRC1, PDGFC, PDLIM3, NTM, and SLC16A3 and downregulation of FBN2 are correlated with a shorter survival time in colon cancer." (PMID 35991839, 2022). "We found that upregulated group of CTHRC1, NTM, PDGFC, PDLIM3, and SLC16A3 genes are consistently correlated with the shorter survival of colon cancer patients in GSE17536." (PMID 35991839, 2022). "Furthermore, the CTHRC1, FBN2, PDGFC, PDLIM3, and NTM genes are positively correlated with the metastatic scores in colon cancer." (PMID 35991839, 2022). "Finally, we investigated the correlation of CTHRC1, FBN2, NTM, PDGFC, PDLIM3, and SLC16A3 with the metastatic scores in colon cancer data." (PMID 35991839, 2022). "Since the expression levels of CTHRC1, FBN2, NTM, PDGFC, PDLIM3, and SLC16A3 are significantly differentiated among the normal samples, primary tumor, and metastatic tumor, we anticipated that these genes are associated with metastasis in colon cancer." (PMID 35991839, 2022). "However, the expression levels of PDLIM3 and SLC16A3 are not significantly altered in colon tumor stroma (p < 0.05) and the expression level of FBN2 showed the opposite trend in the high-CAFs group." (PMID 35991839, 2022).
ovarian carcinoma (3 papers, 2022 to 2025). A malignant neoplasm originating from the surface ovarian epithelium. "Collectively, these insights position PDLIM3 as a potential crucial factor in the prognosis and therapy of ovarian cancer, and our study supports its role as a key protein associated with CP sensitivity in HGSC." (PMID 40697100, 2025). "But understanding the mechanistic involvement of TFRC and PDLIM3 in drug resistance would be a valuable insight into predicting chemotherapy efficacy and guiding therapeutic strategies for ovarian cancer patients." (PMID 40697100, 2025). "Particularly, siRNA-mediated knockdown of seven genes, CASC10, ATP11B, EMP1, GAS1, SLC6A15, GALNT13, and PDLIM3, significantly reduced cell proliferation of ovarian cancer cells." (PMID 35887085, 2022).
Arrhythmia (2 papers, 2022). Any cardiac rhythm other than the normal sinus rhythm. "Additionally, loss of function variants in PDLIM3 have been correlated with atrial fibrillation, a common cardiac arrhythmia, as well as hypertrophic cardiomyopathy." (PMID 36531944, 2022).
atrial fibrillation (2 papers, 2022 to 2025). A disorder characterized by an electrocardiographic finding of a supraventricular arrhythmia characterized by the replacement of consistent P waves by rapid oscillations or fibrillatory waves that vary in size, shape and timing and are accompanied by an irregular ventricular response. "Other studies have also indicated associations of Pdlim3 with atrial fibrillation, myofibrillar myopathy, early regional metastasis of tongue cancer, and invasive bladder urothelial carcinoma involving the muscularis propria." (PMID 40424254, 2025).
colorectal cancer (2 papers, 2014 to 2022). A primary or metastatic malignant neoplasm that affects the colon or rectum. "In a recent study, PDLIM3 was recognized as a potential marker for tumor stroma in colorectal cancer CAFs and classified as one of the genes conferring a high risk of recurrence." (PMID 35647201, 2022).
gastric cancer (2 papers, 2022 to 2025). A primary or metastatic malignant neoplasm involving the stomach. "In one part of this study, we found that upregulation of PDLIM3 expression predicted worse prognosis in association with numerous clinicopathologic features in gastric cancer." (PMID 35647201, 2022). "In summary, elevated expression of PDLIM3 is present in gastric cancer, associated with poor prognosis, high immune cell infiltration, and signal pathway activation." (PMID 35647201, 2022). "Taken together, these results further confirm that increased PDLIM3 expression is a predictive indicator of mortality risk in gastric cancer patients, especially when lymph node metastases are present." (PMID 35647201, 2022). "Thus, all these results imply that PDLIM3 is intimately associated with immune cell infiltration into gastric carcinoma, suggesting that it plays a crucial role in immunologic escape in the gastric cancer microenvironment." (PMID 35647201, 2022). "Thus, upregulation of PDLIM3 was significantly associated with poor prognosis, immune cell infiltration, and activation of two key signal pathways in gastric cancer." (PMID 35647201, 2022). "Based on the results from the GO analysis, we utilized the TIMER2.0 database to explore whether PDLIM3 levels were associated with immune cell infiltrates in gastric carcinoma." (PMID 35647201, 2022). "PDLIM3 was significantly correlated with both immune cell infiltrates and immune-specific marker subsets and two important pathways in gastric cancer." (PMID 35647201, 2022). "The present study indicates that PDLIM3 is a predictive biomarker for immune infiltration in gastric cancer." (PMID 35647201, 2022). "The prognoses of gastric cancer patients were negatively impacted by high PDLIM3 expression, most relevant at later cancer stages, with the highest HR value identified in patients with N1 + 2 + 3 disease." (PMID 35647201, 2022). "As a result, we found that PDLIM3 expression was upgraded in gastric cancer, especially later stages." (PMID 35647201, 2022). "To more deeply explore the correlation between PDLIM3 and tumor-related immune responses in gastric cancer, we found that the expression of this molecule was quantitatively associated with the degree of immune infiltration and specific immunological markers." (PMID 35647201, 2022). "PDLIM3 overexpression was associated with shorter OS and PFS of gastric cancer patients (OS HR = 2.02, P = 9.8e − 10; PFS HR = 1.77, P = 7.5e − 06)." (PMID 35647201, 2022). "In GEO (GSE54129, GSE118916) and the GEPIA database, we found that PDLIM3 mRNA was increased in gastric cancer tissues and later pathological stages." (PMID 35647201, 2022). "Higher levels of PDLIM3 expression, which were paralleled by Her-2 overexpression, differentiation, and the Lauren classification, also influenced the prognosis of gastric cancer patients." (PMID 35647201, 2022). "The mechanisms responsible for PDLIM3 promotion of tumor progression and immune infiltration in gastric carcinoma are yet to be identified and are the subject of the present study." (PMID 35647201, 2022). "In another part of the study, we investigated the cellular functions and molecular mechanisms of PDLIM3 in gastric carcinoma, using GO and KEGG analyses." (PMID 35647201, 2022). "To further explore the impact of high PDLIM3 expression on survival, we analysed correlations between PDLIM3 mRNA levels and clinicopathological characteristics of patients with gastric carcinoma." (PMID 35647201, 2022). "Based on these data, we investigated the levels of PDLIM3 in gastric carcinoma via several database analyses and IHC." (PMID 35647201, 2022). "Based on the data from the GEO, GEPIA, and HPA databases, higher PDLIM3 mRNA and protein levels were present in gastric carcinoma than in matched control tissues." (PMID 35647201, 2022).
gastric cancer (continued). "High PDLIM3 expression was found to be correlated with a lower overall survival time in patients with gastric carcinoma (HR = 2.02, 95% CI = 1.6 to 2.54, Cox P = 9.8e − 10)." (PMID 35647201, 2022). "We hypothesize that the PDLIM3 profile plays a role in CAF-mediated extracellular matrix formation in gastric cancer." (PMID 35647201, 2022). "We propose that PDLIM3 could be used as a biomarker to predict prognosis and immune cell infiltration in gastric cancer." (PMID 35647201, 2022). "Tumor cell migration is mediated by immune and tumor cell interactions via CCL2-CCR2, which might reflect the tumor-promoting effect of PDLIM3 in facilitating the infiltration of TAMs into gastric cancer." (PMID 35647201, 2022). "Therefore, PDLIM3 acts as a potential biomarker and participant in tumor immunity in gastric carcinoma." (PMID 35647201, 2022). "However, correlations between PDLIM3 expression, prognosis, and tumor-infiltrating immune cells in gastric cancer are unknown." (PMID 35647201, 2022). "PDLIM3 was also positively correlated with worse OS and PFS according to gastric cancer staging, Her-2 overexpression, differentiation grade, and Lauren classification." (PMID 35647201, 2022). "We therefore sought correlations between PDLIM3 and crucial markers of the p38 MAPK and ERK MAPK pathways in gastric cancer." (PMID 35647201, 2022). "We found that PDLIM3 expression was positively correlated with such markers including PI3K, PTEN, PKB-γ, and BRAF in gastric cancer." (PMID 35647201, 2022). "Based on the results of the KEGG analysis, we sought correlations between the PDLIM3 level and activation status of the PI3K/Akt pathway, well known for its important impact on the development of gastric carcinoma." (PMID 35647201, 2022). "In order to further validate this result, PDLIM3 expression was shown to be higher in gastric carcinoma than in matched nontumor samples of 15 paired clinical specimens by IHC." (PMID 35647201, 2022). "Third, the HPA database analysis revealed that PDLIM3 expression at the protein levels was higher in gastric carcinoma than in nontumor tissues." (PMID 35647201, 2022). "Gastric cancer tissues were found to express more PDLIM3 than nontumor tissues." (PMID 35647201, 2022). "Therefore, crosstalk between PDLIM3 and PI3K/Akt, p38 MAPK pathways may be the mechanism responsible for correlations between PDLIM3 and poorer prognosis and immune infiltration in gastric cancer." (PMID 35647201, 2022). "Also in the GEPIA gastric carcinoma tissues, PDLIM3 was shown to be elevated in tumors (n = 408) compared to nontumor tissues (n = 211) (P < 0.05), with differences seen in different pathological stages (Pr = 0.000206)." (PMID 35647201, 2022).
hypertrophic cardiomyopathies (2 papers, 2022). "Intrudingly, we identified Pdlim3 and Ldb3 as oxygen-sensitive genes that are associated with hypertrophic cardiomyopathies." (PMID 35326510, 2022).
lymph node metastases (2 papers, 2022 to 2025). "The univariate Cox analysis revealed that age (HR = 1.027, p = 0.033), differentiation (HR = 0.378, p = 0.019), TNM stage (HR = 2.377, p = 0.006), lymph node metastasis (HR = 3.122, p < 0.001), and PDLIM3 expression (HR = 0.419, p = 0.005) may be prognostic factors." (PMID 40243891, 2025).